PDXDC1 (pyridoxal dependent decarboxylase domain containing 1)
Synonyms: KIAA0251; LP8165
Tractability: PROTAC: ubiquitination databases record sites on it; its protein half-life has been measured.
Gene: Protein-coding gene on chromosome 16 (14,974,591 to 15,153,671, forward strand). Ensembl gene ENSG00000179889.
Subcellular location (Human Protein Atlas): Golgi apparatus; Vesicles
Gene Ontology:
Molecular function: cadherin binding; carbon-carbon lyase activity; pyridoxal phosphate binding
Cellular component: Golgi apparatus
Genetic constraint (gnomAD): Loss-of-function variants: 35 observed, 73.16 expected, observed/expected ratio (o/e) 0.48, 90% interval 0.36 to 0.63. The upper end of that interval is the gene's LOEUF score, 0.63, which puts it in group 2 of 6, group 1 being the genes least tolerant of losing a copy. Missense variants: 570 observed, 755.36 expected, observed/expected ratio (o/e) 0.75, 90% interval 0.7 to 0.81. Synonymous variants: 234 observed, 278.94 expected, observed/expected ratio (o/e) 0.84, 90% interval 0.75 to 0.94.
Homologues: Orthologues: macaque PDXDC1 (95% identical), dog PDXDC1 (91% identical), guinea pig PDXDC1 (90% identical), mouse Pdxdc1 (88% identical), pig PDXDC1 (87% identical), rat Pdxdc1 (87% identical), rabbit PDXDC1 (81% identical), tropical clawed frog pdxdc1 (65% identical), zebrafish pdxdc1 (59% identical), Drosophila melanogaster CG1486 (30% identical), Caenorhabditis elegans C14H10.3 (24% identical). Paralogues in human: HDC (13% identical), CSAD (12% identical), DDC (12% identical), GAD1 (12% identical), GAD2 (12% identical), GADL1 (10% identical), SGPL1 (8% identical).
Diseases named in the same sentence as PDXDC1 in open-access papers:
PDXDC1 is named in the same sentence as 10 diseases in open-access papers, as found by Europe PMC text mining. Sharing a sentence is not in itself a finding about the gene and the disease. The quoted sentences say what the papers report.
hearing loss (2 papers, 2014 to 2024). "PDXDC1 gene was frequently deleted in hearing loss patients and modulates prepulse inhibition of acoustic startle in the mouse." (PMID 39315310, 2024). "Additionally, a novel region on chromosome 16 containing part of the PDXDC1 gene was found to be frequently deleted in hearing loss patients (OR = 3.91, 95% CI: 1.62-9.40, p = 1.45 × 10-7)." (PMID 25528277, 2014).
Insulin resistance (1 paper, 2023). Increased resistance towards insulin, that is, diminished effectiveness of insulin in reducing blood glucose levels. "These events suggest PDXDC1 plays a role in the fatty acids metabolism to influence phosphatidylcholine biosynthesis, regulating the risk of insulin resistance and T2D." (PMID 36837846, 2023). "Insulin-resistance in mice induced by high-fat diets showed downregulation PDXDC1 in the liver." (PMID 36837846, 2023).
renal carcinoma (1 paper, 2016). A carcinoma arising from the epithelium of the renal parenchyma or the renal pelvis. "However, a RNA polymerase I-specific transcription initiation factor (RRN3) and PDXDC1, a gene with carboxylase activity associated with diverse phenotypes including renal carcinoma and sensorineural hearing loss were also either proximate to or overlapping the peak in CMS1-FDR signal." (PMID 26943675, 2016).
cancer (2 papers, 2015 to 2022). A tumor composed of atypical neoplastic, often pleomorphic cells that invade other tissues. "Six genes (PDXDC1, ATF7IP2, LIN7C JTB, TTL, DVL2), which regulate the ERG signal transduction pathways, were retained in 4 out of 9 LT patients, were significantly involved in transcriptional mis-regulation in cancer (multiple testing adjusted p-value = 0.025)." (PMID 35773268, 2022).
PDXDC1 also shares sentences with these, for which no sentence is quoted: schizophrenia (2 papers); autism (1); breast carcinoma (1); Intellectual disability (1); metabolic syndrome (1); sensorineural hearing loss (1).